KRAS (KRas proto-oncogene, GTPase)
Diseases named in the same sentence as KRAS in open-access papers (continued):
Sharing a sentence is not in itself a finding about the gene and the disease.
tumor (continued). "Similarly, KRAS mutation (2.6%) independent of tumor tissue has been reported previously in healthy subjects." (PMID 33915745, 2021). "Therefore, inhibiting KRAS directly is a great challenge for KRAS-mutant tumor treatment." (PMID 34742312, 2021). "In conclusion, inducing KRAS degradation could be an alternative way of controlling tumor growth." (PMID 34944952, 2021). "However, a number of aspects remains to be fully understood, and modulating this tumor niche might revert the immunoresistance of KRAS mutant tumors." (PMID 33777798, 2021). "Similarly combining KRAS inhibitors with immune checkpoint inhibitors could improve their efficacy by modulating the tumour microenvironment and increased the sensitivity to checkpoint inhibitors." (PMID 34064232, 2021). "Patients without a pretreatment liquid biopsy (N = 32) and patients carrying a tumor with a KRAS mutation that could not be detected by the ddPCR kits (N = 2) were excluded, leaving 122 ctDNA samples for liquid biopsy analyses." (PMID 34820593, 2021). "As for the tumor counterpart, tissue derived from P12 harbored a PIK3CA missense mutation (chr3_178928067_C_A), two APC stop-gain mutations (chr5_112173917_C_T; chr5_112175951_ G_T), a PTEN stop-gain mutation (chr10_8972066_8972078dup), and a KRAS missense mutation (chr12:_25398284_C_A)." (PMID 34154611, 2021). "In addition to a panel of gene analysis of the tumour, mutation analysis of the BRAF, KRAS and NRAS genes and Mismatch Repair (MMR) status (Microsatellite instability, MSI, Immunohistochemistry, IHC, for MMR genes) will be performed on the selected tumour sections." (PMID 34544470, 2021). "Thus, targeting mutant KRAS may be an optional approach to abolish tumor immune evasion, and combination treatments including KRAS G12C inhibitors and immune checkpoint inhibitors could be effective therapeutic strategies." (PMID 34885068, 2021). "An interesting new role has been proposed for miR-148a-3p, a tumor suppressor microRNA which controls cell proliferation by reducing the expression of SOS2; in KRAS-mutated cells this microRNA is commonly lost, representing a possible new target in KRAS-mutant NSCLC." (PMID 35004317, 2021). "Moreover, lower SDPR expression was observed in KRAS-mutant tumor tissues (P < 0.05)." (PMID 33435990, 2021). "However, less than 10% of PDAC patients harbor an actionable somatic or germline biomarker, including microsatellite stability high (MSI-H), high tumor mutational burden (TMB), BRCA1/2, BRAF V600E, KRAS G12C, HER2, or activating fusions, generally observed in KRAS wild type tumors." (PMID 35083150, 2021). "Thus, interfering with the PS exchange between the PM and the ER effectively depletes PS contents in the PM, compromises the nanoclustering and function of oncogenic mutant KRAS and specifically attenuates the tumor activities of the KRAS-dependent tumor cells." (PMID 34680072, 2021).
tumor (continued). "Based on our previous data and reports from others suggesting that the p110 CUX1 variant induces tumor-promoting signaling pathways, we aimed to establish a conditional mouse model expressing p110 CUX1 to investigate its effects on PDAC formation in context with KRAS." (PMID 34070180, 2021). "The anti-tumor trend of the PERK inhibitor in WT KRAS tumor cells with low ISR may be explained by the implication of PERK in p-eIF2 independent pathways like the stimulation of the nuclear factor erythroid 2-related factor 2 (NRF2)-HIF pathway in pancreatic and lung cancers." (PMID 34330898, 2021). "Importantly, KRAS mutations were not implicated in the modulation of the tumor immune microenvironment in this study." (PMID 34831355, 2021). "Inactivating mutation in SMAD4 does not initiate the tumour genes in PDAC but serve as secondary genetic alterations following KRAS mutation, which was consistent with our genomic finding that both KRAS and SMAD4 had higher mutation frequency in pancreatic body/tail cancers." (PMID 33452856, 2021). "In this study, we also reported miR-16 as significantly downregulated in NSCLC tumor tissues compared to the adjacent lung normal tissue counterparts, and we found that the levels of miR-16 are significantly reduced in KRAS-mutated primary NSCLC compared to KRAS-nonmutated NSCLC." (PMID 34948154, 2021). "Therefore, the relationship between each mutant KRAS allele and the magnitude of the role of mutant KRAS in tumor cell survival are not fully characterized." (PMID 34680229, 2021). "Furthermore, tumor initiating cells in KRAS KO cells were almost half of that in KRAS intact cells." (PMID 34781949, 2021). "Several factors negatively correlated with ASR after thermal ablation of CRLM have been identified in multivariable models, including tumor size, prior liver resection, carcinoembryonic antigen (CEA) levels, proximity to larger intrahepatic vessels, and mutational status of KRAS oncogenes." (PMID 34868968, 2021). "Because all molecular determinations were performed on tumor specimens resected after nCRT, the association between KRAS status and pCR (ypT0–ypN0) could not be analyzed in this study." (PMID 32949260, 2021). "Similarly, ITGBL1 is involved in tumor cell invasion and metastasis through the KRAS/EMT pathway." (PMID 33718128, 2021). "In both univariate and multivariate analyses, a high rate of KRAS exon 2 mutation was associated with the following factors: female sex, advanced age, right-colon tumor, high carcinoembryonic antigen (CEA) levels, stage IV tumor, tumor type histology, and extranodal tumor deposit." (PMID 34335949, 2021). "One patient had CD4+ reactivity from blood (but not tumour) to the KRAS-G12V-mutant allele." (PMID 34200676, 2021). "In CA IX-positive KRAS-mutant PaCa83–2 patient-derived xenografts, 16 weeks of administration of the drug combination resulted in a dramatic increase in survival, as 100% of mice given the combination were alive, with one animal remaining tumor-free after the treatment." (PMID 34948200, 2021). "In the multivariable analysis, the 48 patients with tumor diameters that maintained a < 20% increase from baseline had significantly reduced hazards of death (HR = 0.15, P = 0.01) after adjusting for age, combined surgery, KRAS status, cancer type, MMR, treatment course and cancer differentiation." (PMID 34798858, 2021).
tumor (continued). "Next, 48 patients with tumor diameter that maintained a < 20% increase from baseline had significantly reduced hazards of death (HR = 0.15, P = 0.01) after adjusting for age, combined surgery, KRAS status, cancer type, MMR, treatment course and cancer differentiation using multivariable analysis." (PMID 34798858, 2021). "Higher proportion of EOCRC (54%) harbored KRAS mutation, independent of tumor stage." (PMID 34966694, 2021). "In addition, others have reported emergence of KRAS mutations in liver metastases not detectable in the colonic biopsy, highlighting the role of intra-tumour heterogeneity as a major contributing factor for intrinsic and/or acquired resistance." (PMID 33562755, 2021). "However, the combined treatment inhibited tumor growth and lymph node metastasis in KRAS mutants." (PMID 34641334, 2021). "Using mutant KRAS-driven pancreatic ductal adenocarcinoma (PDAC) mouse models, we show that loss of TIGAR delays the emergence of premalignant pancreatic intraepithelial neoplasia (PanIN) lesions, but enhances the metastatic capacity of the tumor cells, leading to decreased survival." (PMID 31983610, 2020). "Furthermore, tumours without KRAS gene mutation show overexpression of ALDOB and CPS1 and downregulation of PGAM4 genes, which are involved in metabolic pathways such as biosynthesis of amino acids, gluconeogenesis, glycolysis and carbon metabolism." (PMID 31949199, 2020). "However, the (P)RR-expressing HPDE-1/E6E7 cell population began to form a tumour at 5 weeks after implantation, although explosive cell population growth was absent, owing to the absence of mutations in KRAS codons." (PMID 33247206, 2020). "However, only 40–60% of patients with wild type KRAS tumours respond to anti EGFR therapy." (PMID 32594310, 2020). "Interestingly, a recent report identified KRAS codon 61 mutations as arising specifically under therapeutic selection, rather than as direct tumor initiators." (PMID 32634121, 2020). "Of note, this role is appreciable only in oncogene-driven genetic backgrounds (i.e., KRAS-mutated cells), thus suggesting that LKB1 loss might occur as a secondary oncogenic lesion that facilitates tumor progression in cells with one constitutively active oncogene." (PMID 33202760, 2020). "It is not clear, however, whether all KRAS-mutated tumours exhibit an increase in cardiolipin levels in mitochondria." (PMID 31819197, 2020). "Another limitation is represented by the fact that our study did not include systematic analysis of baseline KRAS mutation either in plasma or in tissue, which could unravel the multi-clonal character of the tumours." (PMID 33520716, 2020). "Thus, SNORD50A/B act as tumor suppressors probably by preventing KRas activation." (PMID 32111002, 2020). "In mice, high-fat diet stimulates oncogenic KRAS via cyclooxygenase 2 (COX2) activation, leading to pancreatic inflammation, fibrosis, and development of invasive PDAC, whereas fibroblast growth factor 21, a metabolic regulator preventing obesity, causes reduction in tumor growth." (PMID 32252351, 2020). "Subgroup sample size may have limited the detection of small to moderate risk associations but, taken together, our findings do not support a major role for these biomarkers in the development of specific subtypes of CRC based on KRAS and BRAF mutations or MSI status in the tumor." (PMID 32210264, 2020). "In the tumor group, the five gene sets included Notch signaling (P-value<0.001, ES = 0.61), inflammatory response (P-value<0.001, ES = 0.58), coagulation (P-value = 0.035, ES = 0.57), KRAS signaling (P-value = 0.04, ES = 0.46), and allograft rejection (P-value = 0.041, ES = 60)." (PMID 32496505, 2020).
tumor (continued). "However, how different KRAS variants impact tumor initiation and progression in vivo has not been thoroughly examined." (PMID 33244099, 2020). "The immunohistochemical analysis as well as KRAS mutation analysis indicated that DAC might have arisen from ACC through transdifferentiation, although further case studies are required to clarify the histogenesis of this rare type of tumor." (PMID 32891173, 2020). "The tumour mutational profile identified no mutations in the KRAS, NRAS or BRAF genes." (PMID 32899374, 2020). "In the CRYSTAL study, the addition of cetuximab to the regimen with folinic acid, 5-fluorouracil and irinotecan (FOLFIRI) showed an increase in the response rate (57% versus 40%; p < 0.001) and median OS (23.5 versus 20.0 months; HR 0.796; p = 0.0093) in patients with tumours without KRAS mutations." (PMID 32418154, 2020). "In addition, they indicated that, the detection rates of PIK3CA and/or KRAS ctDNA mutations were associated with the advanced stage; however, they were not related to the histologic subtype or residual tumor status." (PMID 33076944, 2020). "While the chemical inhibitor-based targeting of this mutational KRAS is under clinical trial investigation, there remains a lack of an effective therapeutic strategy for treating NSCLC tumors carrying non G/C substitutions of KRAS or with co-activation of other oncogenes or tumor suppressors." (PMID 32793596, 2020). "Moreover, KRAS expression was stronger in tumors that arose from CLD caused by HBV or HCV than in those of nonviral etiology or in cirrhotic parenchyma without tumor." (PMID 33178273, 2020). "Therefore, considering that increased FDG uptake is associated with aggressive tumor characteristics and negative prognostic effect, increased SUVmax in the presence of KRAS mutations was interpreted as a poor prognostic factor." (PMID 32079384, 2020). "In this context, the absence of KRAS mutation at baseline might be not only related to technical limits but also to biological reasons, such as tumour burden and levels of tumour shedding." (PMID 32376889, 2020). "In future studies, it will be important to identify tumour-specific KRAS-induced mechanisms, in order to specifically identify and stratify patients that might benefit from suppression of tumour-promoting inflammation or immunotherapies for the eventual success of KRAS-targeted therapies." (PMID 33116132, 2020). "While the effects of tumor mutation burden (TMB) and copy number alteration (CNA) are poorly understood in this illness, our study aimed to explore the roles TMB and CNA play in the prediction of response to immune checkpoint inhibitor (ICI) therapy in advanced KRAS-mutant LUAD." (PMID 33072585, 2020). "Importantly, GSEA analysis of RNA-seq data demonstrated that knockdown circPRRC2A correlates significantly with downregulation of EMT target genes, also confirmed that circPRRC2A is positively correlated with tumor angiogenesis and negatively correlated with the KRAS and TNF-α pathways." (PMID 32292503, 2020).
tumor (continued). "Research has been shown that cancer cells with KRAS mutation are more sensitive to PLK1 inhibitors than KRAS wild-type cancers, suggesting that KRAS mutation induces mitotic stress in tumor cells and may underlie tumor sensitivity to anti-mitotic agents." (PMID 32486290, 2020). "Targeting KRAS could sensitize tumor cells to chemotherapy in CRC and other cancers." (PMID 33072545, 2020). "Analysis of tumor gene expression data sets has shown that mutant KRAS status is associated with reduced infiltration of cytotoxic T cells and suppression of the adaptive IFN-γ response in CRC, and a possible mechanism for mutant KRAS-driven CRC immune tolerance was recently reported." (PMID 31893287, 2020). "A prospective phase II study found that approximately 50% of the metastatic CRC patients on trial that were identified without KRAS mutations after the tumor biopsy were shown to actually contain RAS aberrations and did not benefit from anti-EGFR monoclonal antibody treatment." (PMID 32471160, 2020). "Also, tumor localization and the presence of KRAS mutation had no statistically significant impact on mortality." (PMID 32079384, 2020). "In addition to KRAS, other components like BRAF, MEK, and MAPK1 are also involved and mutation in one of them leads to a constitutive activation of MAPK/ERK signaling pathway that ultimately results in neoplasm." (PMID 32612457, 2020). "Further studies into anti-tumor activities against EGFR-expressing CRC cells are necessary in order to obtain a more detailed understanding of antibody therapy against CRC cells with KRAS p.G13D, which will lead to the development of more effective clinical treatments." (PMID 32839411, 2020). "Therefore, we thought that the eraser gene FTO might down-regulate the m6A level of key molecules in KRAS signaling and further activate KRAS signaling to promote tumor." (PMID 32903217, 2020). "Furthermore we did not detect any mutations in KRAS in any of the sorted tumor populations from each patient." (PMID 30870501, 2019). "Notably, however, tumor spread through air spaces (STAS) and “tumor islands” are closely related morphological features to vessel cooption and were found to be significantly associated with KRAS mutations in NSCLC." (PMID 31600989, 2019). "Most juice samples exhibited multiple KRAS variants not seen in the primary tumor, and only in 11 cases (52%) did the most abundant variant of the juice correspond to the KRAS mutation detected in the tumor." (PMID 30611220, 2019). "For KRAS mutation discrepancies, tissue heterogeneity where a rare mutated clone would have been detected in a specific region of the tumour but not found in the plasma sample could also be a relevant explanation." (PMID 30585255, 2019). "Our results showed that KRAS MAF in ctDNA might be a good indicator of tumor burden in PC." (PMID 31850201, 2019). "SNARE TKO reduced active AKT and ERK signaling in xenografted tumors driven by oncogenic KRAS and reduced tumor size by the oncogenic KRAS mutant subclone down to that seen with the KRAS WT isogenic line, which still formed tumors of comparable size whether SNAREs were knocked out or not." (PMID 31712554, 2019). "Moreover, when the mutation found in the tumor was absent from the juice, other KRAS mutations were usually present." (PMID 30611220, 2019). "To determine whether the regulatory effects of miR-873 on proliferation, invasion, and migration in PDAC and TNBC cells are mediated by KRAS, we used small interfering RNA (siRNA)-mediated KRAS inhibition to recapitulate the tumor suppressor effects of miR-873 in PDAC and TNBC cells." (PMID 30654191, 2019). "PCC0208027 and other EGFR TKIs showed no anti-tumor activity against A549 cells with KRAS mutation." (PMID 30952931, 2019).